PTPRC (protein tyrosine phosphatase receptor type C)
Diseases named in the same sentence as PTPRC in open-access papers (continued):
Sharing a sentence is not in itself a finding about the gene and the disease.
lupus (44 papers, 2011 to 2025). "Of note, the lupus-susceptibility risk loci PTPRC, NCF1 and ITGAM genes, as well as the IRF8,33–35 emerged as hub network genes, suggesting a pathogenic role during evolution from preclinical to clinical LN." (PMID 35906002, 2022). "In this process, we identified pathways enriched within each signature and found that hub genes correspond to lupus susceptibility risk loci (such as the PTPRC, ITGAM, NCF1 and IRF8 genes), reinforcing their pathogenic role in LN and the progression from preclinical to clinical kidney disease." (PMID 35906002, 2022). "In a co-aggregation gene study involving autoimmune diseases such as primary Sjogren’s syndrome, systemic lupus erythematosus, and rheumatoid arthritis, PTPRC was found to exhibit significant differential protein expression in all three disease types." (PMID 39301055, 2024). "As a gene closely related to immune function, PTPRC has consistently been reported to be related to autoimmune diseases such as systemic lupus erythematosus and multiple sclerosis." (PMID 37996489, 2023). "A previous study has found that PTPRC activates JAK and STAT proteins by suppressing JAK kinase, leading to autoimmune disorder in systemic lupus erythematosus." (PMID 32662826, 2020).
B-cell lymphoma (43 papers, 2008 to 2026). "previously developed CD45er, a script for the analysis of PTPRC/CD45 splicing in scRNA-seq data to evaluate engineered T cells in B-cell lymphoma therapy." (PMID 39445006, 2024).
prostate carcinoma (43 papers, 2012 to 2026). A carcinoma that arises from epithelial cells of the prostate gland. "To identify metastasis-specific alterations in the composition and gene expression of KP_Pos (KRT18+PTPRC+) cells, we conducted an integrated single-cell transcriptomic analysis of benign, primary, and metastatic prostate cancer tissues." (PMID 41355965, 2026). "In more advanced type of prostate cancer (MCRPC), splice-disrupt variants, located on CDs of NCOR2, PTPRC, and CRP, are the high-risk variants." (PMID 35286517, 2022). "A multiplex TaqMan assay targeting VIM and PTPRC transcripts should identify both lymphocyte and prostate cancer cell types used in our spike-in experiments." (PMID 27189161, 2016). "We showed that a VIM+/PTPRC- multiplex TaqMan assay run on the PACS workflow enables high-fidelity identification of prostate cancer cells from both a background cell line or primary cell population." (PMID 27189161, 2016). "Splice-disrupt variants on CTSF and PTPRC is specific to MCRPC and may contribute to prostate cancer progression." (PMID 35286517, 2022). "We found that splice-disrupt variants on CTSF and PTPRC is specific to MCRPC and may contribute to prostate cancer progression." (PMID 35286517, 2022).
atherosclerosis (39 papers, 2011 to 2026). A disease characterized by the build-up of fatty material and calcium deposition in the arterial wall resulting in partial or complete occlusion of the arterial lumen. "Bioinformatic and correlation analyses of differentially expressed immune cells helped to identify CCL4, TLR2, IL1B, and PTPRC as hub genes in atherosclerosis formation and plaque progression." (PMID 35509837, 2022). "As a critical antigen, T cell activation in atherosclerosis relies on PTPRC, previously known as CD45." (PMID 37521843, 2022). "Based on the correlation criteria and correlation criteria value, CCL2, CCL4, TLR2, IL1B and PTPRC were identified as hub immune genes in atherosclerosis." (PMID 35509837, 2022). "Nie reported that PTPRC was considered to be an immune marker gene in atherosclerosis development." (PMID 37179331, 2023). "In addition, CCL4, TLR2, IL1B and PTPRC were considered to be immune marker genes in atherosclerosis development." (PMID 35509837, 2022). "have demonstrated that PTPRC could act as a regulatory T cell (Treg)-related gene in the progression of atherosclerosis in previous bioinformatics analysis, yet there is still a lack of directly experiment evidence that PTPRC is correlated with atherosclerotic plaque evolution." (PMID 36311761, 2022). "Therefore, considering its role in RA and atherosclerosis, PTPRC is a possible treatment target." (PMID 35304503, 2022). "Within the shared CAD/atherosclerosis liver network between species, APBB1IP, PTPRC, NCKAP1L and INPP5D were captured as potential novel KDs which again have not been strongly investigated, validated or implicated in CAD previously." (PMID 38060277, 2023). "Among the hub genes, TNF, PTPRC (also known as CD45), VCAM1, CD86 and MMP9 have been confirmed as inflammatory biomarkers of atherosclerosis." (PMID 32213192, 2020).
pancreatic cancer (39 papers, 2012 to 2025). "Database analyses also revealed a significant negative correlation between ITGB4 and PTPRC (CD45 gene), CCR5 as well as CCR1 in pancreatic cancer, but not normal pancreas tissue." (PMID 36932441, 2023). "Finally, the TCGA and GTEx databases were used to verify a weak, but significant inverse correlation of CD45 (PTPRC gene), CCR5 and CCR1 with ITGB4 in human pancreatic cancer, but not normal pancreas." (PMID 36932441, 2023).
Sepsis (39 papers, 2006 to 2026). Sepsis is defined as life-threatening organ dysfunction caused by a dysregulated host response to infection. "PTPRC, also known as CD45, is implicated in apoptosis in ARDS and is a potential therapeutic target for sepsis, with regulation by 4‐octyl itaconate enhancing antimicrobial effects." (PMID 39854144, 2025). "Our study identified DE‐PRGs—NDRG1, DDX3X, PTPRC, and TNFSF8—in patients with sepsis‐associated ARDS." (PMID 39854144, 2025). "The analysis showed that NOS3, SIRT1, HSP90AA1, MMP9, MMP2, PTPRC, and TLR2 were associated with multiple organ damage in sepsis." (PMID 36406124, 2022). "This study identifies four key PANoptosis‐related genes (NDRG1, DDX3X, PTPRC, and TNFSF8) that are differentially expressed in sepsis and septic ARDS." (PMID 39854144, 2025).
asthma (38 papers, 2011 to 2025). "PTPRC previously shown to be upregulated in brain of mice following infection of prion, is associated with asthma related phenotypes and its ligation enhances the frequency of constitutive apoptosis in human eosinophils." (PMID 34394070, 2021). "PTPRC was found to be associated with asthma related phenotypes in a microarray analysis." (PMID 34394070, 2021). "iPathway also identified differential methylation of upstream mediators such as PTPRC that might regulate other genes downstream or differential methylation of a family of genes including olfactory receptors, some of which have been implicated in asthma." (PMID 39380119, 2024). "Our study, therefore, builds on existing evidence that PTPRC, and its downstream gene pathway, is important in the asthma pathogenesis." (PMID 38129444, 2023). "Despite using a different analytical method, applied to a different cell type, they also identified PTPRC as a master regulator of a persistent asthma module, which was enriched in inflammatory response pathways." (PMID 38129444, 2023). "Consistent with our findings (i.e. higher expression of PTPRC in asthmatics), eQTLs reported in GENCORD to be associated with increased expression of PTPRC are also reported to increase the risk of asthma in GWAS studies." (PMID 38129444, 2023). "By integrating publicly available genetic and protein–protein interaction data, we identified PTPRC, a gene previously identified as a master regulator of asthma gene expression profile from nasal brushing, as a master regulator in peripheral CD4+ T-cells." (PMID 38129444, 2023). "Through integration of publicly available eQTL and GWAS summary statistics (colocalisation), and protein–protein interaction (PPI) data, we identified PTPRC, a potential druggable target, as a putative master regulator of the asthma gene-expression profiles." (PMID 38129444, 2023). "Notable genes that were differentially methylated based on asthma severity included RUNX3, several members of the HLA family, AGT, PTPRC, PTPRJ, and several genes downstream of the JAK2 and TNF signaling pathway." (PMID 39380119, 2024). "We identified PTPRC, a gene previously identified in GWAS studies, which also showed evidence of colocalisation with T-cell specific eQTL from GENCORD, as a putative master regulator in CD4+ T-cell asthma gene expression profile." (PMID 38129444, 2023).
colon carcinoma (38 papers, 1989 to 2025). "Lymphocyte antigen 6 complex locus G6D (LY6G), protein tyrosine phosphatase receptor type C (CD45), and adhesion G protein-coupled receptor E1 (F4/80) are used as inflammatory infiltration marker for colon cancer progression and metastasis marker." (PMID 32131398, 2020). "The role of PTPRC has also been noticed in colon cancer metastasis." (PMID 35286517, 2022). "No other studies have reported an association between PTPRC and colon cancer metastasis." (PMID 28629469, 2017). "CHI3L1, PTPRC, and ITGAM, three key genes in colon cancer proliferation and metastasis, demonstrated the highest baseline expression and significant changes in gene expression." (PMID 38037545, 2023). "Therefore, APBB1IP, LCP2, and PTPRC might also play a role in colon cancer metastasis." (PMID 28629469, 2017). "This is the first evidence supporting a role for PTPRC, APBB1IP, LCP2, miR-30a-3p, and miR-30e-3p in colon cancer metastasis." (PMID 28629469, 2017). "It is reported that PTPRC was predicted to interact with CXCR4, and PTPRC might also play a role in colon cancer metastasis." (PMID 30587197, 2018). "As PTPRC was predicted to interact with CXCR4, we speculated that PTPRC may also be involved in the metastasis of colon cancer to the liver." (PMID 28629469, 2017).
viral infection (38 papers, 2010 to 2025). "In addition, there is sufficient evidence that PTPRC acts as an important regulator of immune cell function, protection against viral infection, and is associated with immunodeficiency and viral susceptibility." (PMID 35145474, 2021). "On the other hand in SCGB1A1-hACE2 mice, the innate immune cells including F4/80 positive macrophages alone could not contain the level of virus infection at 2dpi, which led the increased number of PTPRC and CD3 positive adaptive immune cells at 5, 7dpi." (PMID 36457995, 2022).
Immunodeficiency (32 papers, 2012 to 2025). Failure of the immune system to protect the body adequately from infection, due to the absence or insufficiency of some component process or substance. "The PTPRC protein is necessary for T-cell activation, and its mutation is associated with severe combined immunodeficiency." (PMID 33968341, 2021). "Loss-of-function mutations of PTPRC have consequences related to immunodeficiency and malignancy in humans and mice and CD45 has been associated with disease in cattle." (PMID 34305905, 2021). "Disruption of PTPRC balance can lead to immune deficiencies, autoimmune diseases, or malignancies." (PMID 40777026, 2025). "PTPRC also plays an important role in autoimmune diseases and cancers, as well as in infectious diseases; its deficiency may lead to T and B lymphocyte dysfunction, manifesting as severe combined immunodeficiency." (PMID 35515499, 2022). "PTPRC gene is an essential regulator of T and B cell antigen receptor-mediated activation, and its dysfunction can result in immunodeficiency, autoimmunity, or malignancy." (PMID 36552740, 2022). "With respect to the immune response, up-regulated proteins (like FGA) were pro-inflammatory, while down-regulated proteins participated in antigen processing and antigen presenting (like MYO1G), immunoglobulin and cathelicidin production (like fowlicidin-2), and immunodeficiency (like PTPRC)." (PMID 27761697, 2016). "Downregulated genes in CD69+ CD4+ T cells were involved in cell adhesion (PTPRC; -0.38log2FC), differentiation (CD44; -0.38log2FC), and immunodeficiency (IL7R; -0.42log2FC) pathways." (PMID 41208955, 2025). "A series of TME-related prognostic genes were acquired in this research, which could reflect immune disorders within TME, and PTPRC and CD19 show the potential to be an indicator for LUAD prognosis and tumor microenvironment modulation." (PMID 33520448, 2021).
diabetes (31 papers, 2012 to 2026). "These previous findings and our findings support the hypothesis that upregulation of PTPRC regulates viral susceptibility and immune cell function and contributes to the pathogenesis of PD and diabetes." (PMID 35145474, 2021). "In diabetes, protein tyrosine phosphatase is known to act as a negative regulator of insulin signaling, and expression of PTPRC is associated with residual β-cell function in type 1 diabetes." (PMID 35145474, 2021). "Moreover, it was shown that the expression of PTPRC was related to residual β-cell function in type 1 diabetes mellitus." (PMID 31783860, 2019).
autoimmune disease (28 papers, 2010 to 2025). A disorder resulting from loss of function or tissue destruction of an organ or multiple organs, arising from humoral or cellular immune responses of the individual to their own tissue constituents. "Additionally, genetic studies on HT have identified specific variations in the PTPRC gene that increase susceptibility to autoimmune diseases, such as Type 1 diabetes and Graves’ disease." (PMID 39805933, 2025). "According to these investigations, PTPRC alterations may increase the overall reactivity of the immune system and thus can predispose an individual to many different types of autoimmune diseases, including MS." (PMID 38542346, 2024). "Finally, WES has unveiled potential pathogenic variants in PTPN3 (as well as in PTPRC, to be discussed later) involved in familial autoimmunity diseases." (PMID 36755664, 2022). "By regulating lymphocyte survival, cytokine responses, and TCR signaling, PTPRC controls immune function, and is under investigation as a therapeutic target for various immune‐related conditions, including autoimmune diseases and organ transplantation." (PMID 38899746, 2024). "In the whole-exome sequencing of 31 families with autoimmune disease history, 39 variants in immune-related genes across RA, SLE, and SS patients were concentrated on T cell receptor signaling pathways, and PTPRC is a component of this pathway." (PMID 37727764, 2023). "In our finding, the KEGG and GO pathway suggests PTPRC may have a close relationship between autoimmune diseases and the regulation of T cell activation and the T cell receptor signaling pathway." (PMID 39301055, 2024). "Therefore, PTPRC is considered a typical biomarker for the concomitantly occurring autoimmune disorders and AS." (PMID 37727764, 2023). "Protein tyrosine phosphatase receptor type C (PTPRC) is a member of the PTP family and promotes autoimmune diseases." (PMID 32662826, 2020).
colorectal cancer (26 papers, 2010 to 2026). A primary or metastatic malignant neoplasm that affects the colon or rectum. "In colorectal cancer, a subset of epithelial tumor cells aberrantly expresses PTPRC, and elevated expression in those cells is linked to poor tumor regression and shorter recurrence-free survival after chemoradiotherapy." (PMID 41596598, 2026). "Investigation of DOCK2 and PTPRC somatic mutations in colorectal cancer revealed a fairly high frequency (10% and 8%, respectively) of genetic alterations in tumors." (PMID 33968341, 2021). "As in colorectal cancer, PTPRC drives HGSOC progression by promoting therapy resistance and CSC-related properties." (PMID 41596598, 2026). "PTPRC is also related to tumor necrosis and disrupts normal T- and B-cell signaling through SRC kinase pathways—which are separately implicated in colorectal cancer through amplification." (PMID 31356589, 2019).
gastric cancer (23 papers, 2014 to 2026). A primary or metastatic malignant neoplasm involving the stomach. "The qPCR validation showed that PTPRC, SERPINB9, and RAC2 had low expression in gastric cancer cells, whereas only CCL20 and BANK1 were highly expressed." (PMID 40444282, 2025).
metastatic tumors (21 papers, 2011 to 2024). "Among these, FRAS1, PTPRC, MACF1 and MYH8 mutations have been found to be more enriched in other metastatic tumors." (PMID 36033490, 2022).
Autoimmunity (20 papers, 2007 to 2025). The occurrence of an immune reaction against the organism's own cells or tissues. "In addition, its target gene PTPRC (encoded protein tyrosine phosphatase receptor type C), also known as CD45, is essential for T‐cell antigen receptor‐mediated activation, and its downstream regulatory imbalance can result in autoimmunity." (PMID 35092700, 2022).
endometriosis (20 papers, 2017 to 2025). The growth of functional endometrial tissue in anatomic sites outside the uterine body. "Furthermore, CD45+ (PTPRC+) single-cell sequencing of murine endometriosis-like lesions and peritoneal fluid reveals a recurrent wound healing cycle." (PMID 39385609, 2024).
myocardial infarction (20 papers, 2009 to 2025). Gross necrosis of the myocardium, as a result of interruption of the blood supply to the area, as in coronary thrombosis. "PTPRC (CD45) regulates neutrophil activation and migration post-myocardial infarction." (PMID 40096134, 2025).
psoriasis (18 papers, 2017 to 2025). An autoimmune condition characterized by red, well-delineated plaques with silvery scales that are usually on the extensor surfaces and scalp. "Additionally, earlier bioinformatic analyses have shown that PTPRC is a critical gene in the pathophysiology of AS with psoriasis and rheumatoid arthritis." (PMID 37727764, 2023).
neuroblastoma (17 papers, 2011 to 2025). Neuroblastoma (NB) is the most common solid, extracranial childhood tumor. "To unravel the composition and function of neuroblastoma-infiltrating immune cells we performed an in-depth analysis of the PTPRC+ (CD45+) immune clusters." (PMID 38181797, 2024).